IL6 (interleukin 6)
Diseases named in the same sentence as IL6 in open-access papers (continued):
Sharing a sentence is not in itself a finding about the gene and the disease.
Sepsis (continued). "Changes in IL-6 during the initial days of sepsis have also been associated with mortality in several distinct cohorts." (PMID 32034914, 2021). "While an acute increase in systemic IL-6 promotes muscle growth and hypertrophy, its sustained elevation, as occurring in catabolic conditions such as cancer or sepsis, causes muscle atrophy." (PMID 34572540, 2021). "Upregulation of inflammatory cytokine secretion such as IL-6, in response to pathogens has been linked to an increase risk for sepsis." (PMID 33801785, 2021). "They demonstrated that IL-1β, TNF-α and IL-6 enhance bacterial growth in patients with sepsis-associated ARDS." (PMID 34945111, 2021). "AE and light are also effective in reducing biofilm formations, suppressing NO, IL-1β, IL-6, hemolytic activities, and inhibiting the expressions of toxins that cause sepsis." (PMID 34319262, 2021). "Excessive production of pro-inflammatory cytokines like (TNF-α, IL-1β, and IL-6), chemokines, and other inflammatory molecules are associated with sepsis." (PMID 35005242, 2021). "The prediction model proposed that the “PCT” and “IL-6” variables are important in predicting risk of sepsis." (PMID 34886497, 2021). "Several other studies have shown that the majority of patients with sepsis have elevated IL-6 levels and these levels have been associated with severity and survival expectancy." (PMID 33917002, 2021). "As in Sepsis, which is one of the most common causes of death for hospitalized patients, Interleukin (IL)-6 reaches peak levels rapidly within 2 h after exposure to an infectious stimulus." (PMID 34372196, 2021). "Of all three studied biomarkers, IL-6 showed the weakest diagnostic value for sepsis, with a pooled sensitivity of 0.72 (95% CI, 0.65–0.78), the pooled specificity of 0.70 (95% CI, 0.62–0.76), and AUC of 0.77 (95% CI, 0.73–0.80)." (PMID 33902476, 2021). "Measuring the IL-6 levels in at-risk patients can accurately predict individuals who are at significant risk of death as a result of sepsis." (PMID 34595242, 2021). "In a large multicenter observational study including 583 patients with severe sepsis, it was demonstrated that patients with high levels of IL‐6 and IL‐10 had markedly increased risk of dying (hazard ratio of 20.52)." (PMID 33719215, 2021). "Subsequently, excessive expression of TLR4 caused over-activation of NF-κB and increased release of inflammatory mediators such as TNF-α, IL-6, and IL-8, which can cause tissue injury and even sepsis." (PMID 34712822, 2021). "The pathophysiology of cardiac dysfunction with CRS resembles cardiomyopathy during stress and sepsis, likely associated with IL-6 (interleukin-6), which is usually found as a mediator of myocardial depression in cases of inflammatory and infectious states." (PMID 34681194, 2021). "Compared to control, sepsis was associated with higher levels of IL-6 (median 0.0 pg/ml vs. 703 pg/ml; ***p<0.001) and IL-10 (median 0.0 pg/ml vs. 217 pg/ml; **p<0.01) at the time of study inclusion." (PMID 33939725, 2021). "We show that IL-6 can offer valuable information about the subsequent sepsis severity and risk of mortality among premature neonates suspected of LONS." (PMID 33407770, 2021). "Sepsis caused a significant increase in the expression of IL-6 level in testicular tissue in the sepsis group compared with the sham group (1.65 ± 0.01 vs 0.55 ± 0.01 %, P<0.05)." (PMID 35317115, 2021). "For example, Interleukin-6 (IL-6) is a multifunctional cytokine, and high bloodstream levels of it have been associated with severe inflammatory diseases, such as dengue fever, sepsis, various cancers, and visceral leishmaniasis (VL)." (PMID 34372196, 2021). "A series of inflammatory biomarkers such as CRP, SAA, procalcitonin (PCT) and interleukin 6 (IL-6) have been found to be associated with infectious diseases and have been used to diagnose sepsis." (PMID 34198765, 2021).
Sepsis (continued). "This trend follows through life, with males being more likely to die from sepsis than females, an observation associated with altered ratios of proinflammatory IL-6 and anti-inflammatory IL-10." (PMID 34489958, 2021). "IL-6 is one of the most commonly used biomarkers of sepsis, and the level of IL-6 is positively correlated with sepsis-associated organ dysfunction and death." (PMID 35118141, 2021). "While both asphyxia and sepsis cause increased plasma level of IL-6 concentration, TNF-α level is more associated with sepsis." (PMID 34282369, 2021). "Circulating concentrations of IL-6 cytokine have a prognostic value for the outcome of sepsis patients and previously published studies showed increased susceptibility to systemic candidiasis in IL-6−/− deficient mice." (PMID 34696267, 2021). "A similar study investigated the association of IL-6 and IL-10 levels with mortality in patients with sepsis and septic shock." (PMID 34945111, 2021). "miR-128-3p mimics given before CLP operation effectively alleviated lung damage caused by sepsis, decreased activity of caspase-3 and cell apoptosis, and inhibited induction of IL-1β and IL-6." (PMID 34430706, 2021). "In clinical practice, IL-6 is associated with cardiovascular disease, cancer, osteoporosis, and can be used as a biomarker in sepsis." (PMID 33670858, 2021). "Because the infection is a major side effect associated with tocilizumab treatment, the development of an IL-6 inhibitor with a short half-life for use in the treatment of pathogen-induced cytokine storms, such as those cause by sepsis, is desirable." (PMID 34253862, 2021). "On the other hand, high IL-6 serum levels are a hallmark of imminent death in bacterial infection and sepsis." (PMID 33278000, 2021). "They concluded that IL-6 has relatively high diagnostic accuracy for identification of early-onset sepsis, with an AUC of 0.92." (PMID 32164268, 2020). "Excessive inflammatory response is associated with multiple organ failure and poor outcome in sepsis, and is characterized by enhanced expression of inflammatory factors including IL-1β, IL-6, and TNF-α." (PMID 33324396, 2020). "Our results are consistent with those from a recently published study conducted on sepsis patients which showed that although IL-6 and IL-10 were associated with mortality, the balance between these two cytokines did not impact mortality." (PMID 32015566, 2020). "In sepsis and septic shock patients, upregulation of many cytokines, including IL-1β, IL-6, IL-8, IL-10, MCP-1, and G-CSF, was associated with increased mortality and positively correlated with patients’ SOFA scores." (PMID 32669536, 2020). "Higher concentrations of IL-6 and IL-10 predict higher mortality rates in patients with sepsis; an elevated IL-6/IL-10 ratio is also associated with mortality in these patients." (PMID 33203111, 2020). "Previous studies have reported of raised serum IL-6 levels being associated with sepsis in AKI patients." (PMID 32487191, 2020). "In contrast, there is evidence to suggest that IL-6 release was increased in TRPM2-deficient mice in sepsis model." (PMID 32513195, 2020). "This allowed us to develop a COVID-board learning curve for all team members in trying to differentiate COVID-specific inflammation from other causes of IL-6-driven inflammation (sepsis, superinfection)." (PMID 32518419, 2020). "IL-6 was determined to be implicated in the induction of thrombosis, vascular leakage, and multiple organ dysfunctions during severe sepsis." (PMID 32197507, 2020). "Currently, there is a consensus that imbalance between anti- and pro-inflammatory cytokines e.g. IL-6 and IL-10 is one of the cause of mortality in sepsis." (PMID 32015566, 2020). "MRproADM levels are significantly increased in patients with sepsis, but its diagnostic value for identifying sepsis is numerically lower than that of established markers (e.g., interleukin-6, C-reactive protein, and procalcitonin)." (PMID 32831638, 2020).
Sepsis (continued). "IL-1β and IL-6 were also identified as prognostic indicators for sepsis-associated AKI due to their crucial function in local acute inflammation and acute renal damage." (PMID 32655407, 2020). "Trans-signaling of IL-6 by endothelial cells has been associated with CRS due to other etiologies such as sepsis, acute respiratory distress syndrome (ARDS), and severe burn injuries." (PMID 33643299, 2020). "The serum concentration of IL-6 has been shown to be closely associated with the prognosis of sepsis; levels higher than 500 pg/mL were associated with 11% mortality, whereas levels > 7,500 pg/mL were associated with 37% mortality." (PMID 32273831, 2020). "Considering the crucial role of acute inflammatory responses in the development of sepsis patients, we further evaluated the association of serum miR-19b-3p level with the release of inflammatory factors, including IL-6 and TNF-α." (PMID 32188465, 2020). "A prospective controlled study in 2019 enrolled 142 subjects (51 with sepsis, 46 with septic shock, and 45 controls) and investigated the diagnostic value of IL-6 according to the Sepsis-3 definition." (PMID 33198109, 2020). "Reduction in lactate and elevation in NGAL levels were associated with survival; IL-6 level decrease was observed only in survivors with sepsis." (PMID 32635454, 2020). "In clinical studies, according to Sepsis-3 criteria, the diagnostic and prognostic value of IL-6 was superior to other compared markers for both sepsis and septic shock." (PMID 32842482, 2020). "Hemolysis and elevated IL-6 are associated with disease severity in malaria, sepsis and pre-eclampsia, with cardiac dysfunction as an additional comorbidity in these diseases." (PMID 33584641, 2020). "For instance, IL-6 has been shown to be associated with mortality, and its kinetics is an indicator of therapeutic response in patients with sepsis." (PMID 32635454, 2020). "Unlike other markers, if there are antenatal risk factors for sepsis (such as chorioamnionitis), IL-6 should be determined in the umbilical cord blood, as its concentration rises significantly in the case of infection." (PMID 33419284, 2020). "Recently, IL-6 has been highlighted as a novel diagnostic biomarker for neonatal and adult sepsis in people with a moderate diagnostic accuracy similar to procalcitonin and in dogs with septic peritonitis." (PMID 32548135, 2020). "Sepsis-associated inflammatory cytokines, including IL-6, TNF-α, and IL-10, were significantly elevated in antibiotic-treated Rag2γc mice 12 days post infection compared to their levels in the B6 mice (p < 0.001)." (PMID 33488563, 2020). "Our study included large number of neonates with culture proven sepsis, clinical sepsis, and controls to correctly define the optimal cut-off values and measure the diagnostic performances of IL-6 and CRP." (PMID 33233806, 2020). "IL-6 deficiency preserved cardiac function in 2-month-old mice but was detrimental in 14-month-old mice after burns complicated by sepsis." (PMID 32932869, 2020). "The combined biomarker approach using PTX3, PCT, IL6, and lactate showed good performance in predicting 28-day all-cause mortality among the patients diagnosed with sepsis or septic shock as defined by Sepsis-3." (PMID 32481464, 2020). "Beyond activating the endothelium and leukocytes, TNF-α, IL-1β, and IL-6 combine to induce the systemic acute phase response that is implicated in the development of sepsis." (PMID 32849612, 2020). "Whereas elevation of TNF-α occurs for a short period of time in the initial phase of sepsis, the increased levels of IL-6 occur for longer periods and are associated with increased mortality in septic patients." (PMID 33382782, 2020). "We found that lnc‐MALAT1/miR‐125a axis was positively associated with APACHE II score, SOFA score, Scr, CRP, TNF‐α, IL‐1β, IL‐6, and IL‐8, while negatively associated with albumin in sepsis patients." (PMID 32309886, 2020).
Sepsis (continued). "IL-8, together with other markers like PCT or IL-6, was found to be a reliable diagnostic marker for sepsis or bacteremia and to predict low-risk for bacterial infections." (PMID 32519027, 2020). "High values of IL-10 (cut-off > 208 ng/L) in association with high values of IL–6 (cut-off > 168 ng/L) are suggestive for disseminated intravascular coagulation (DIC) in neonates with sepsis." (PMID 33419284, 2020). "First, the specific DNA methylation profiles of monocytes from patients with sepsis associate with IL-10 and IL-6 levels." (PMID 31665078, 2019). "Some previous studies reported the association between IL-6-174G/C polymorphism and the risk and mortality of sepsis." (PMID 30782124, 2019). "It was also found that IL-6 has an age-associated increase during systemic inflammation so that young persons should have a comparatively low IL-6 level during sepsis." (PMID 30782124, 2019). "This article intends to explore the association between interleukin-6 gene (IL-6) -174 G/C single nucleotide polymorphism (SNP) and the risk and mortality of sepsis by conducting this updated meta-analysis with trial sequential analysis." (PMID 30782124, 2019). "IL-6 was an independent risk factor for 28-day mortality among patients with sepsis and septic shock (HR, 1.0004; 95% CI, 1.0003-1.0005; p=0.024)." (PMID 31243609, 2019). "Several studies have shown that a rapid decrease in IL-6 in sepsis is associated with a better survival rate." (PMID 30760225, 2019). "TNFα directly stimulates hepatocytes to produce IL-6, the major mediator of acute phase response, which is known to be increased in sepsis patients and associated with a higher risk of death." (PMID 30873161, 2019). "The IL6 SNPs rs1800796 and rs1800795 were previously associated with increased incidence of aCA and development of sepsis in children in a study undertaken in Finland." (PMID 30795743, 2019). "IL-6 and IL-8 have been shown to have elevated levels in sepsis, and are also associated with severity and outcome." (PMID 30609860, 2019). "Twenty studies (including 3282 cases and 4926 controls) and eight studies (including 610 cases and 1856 controls) were respectively enrolled in the analysis on the association between IL-6-174 G/C polymorphism and the risk and mortality of sepsis." (PMID 30782124, 2019). "Reports in which IL-6 was a better diagnostic marker for sepsis than PCT, presepsin, and CRP are consistent with our study." (PMID 31718563, 2019). "Inhibition of IL-6 trans-signaling has been shown to protect animal models from developing liver cancer and sepsis-associated mortality." (PMID 31636639, 2019). "Thrombocytopenia in septic patients and platelet depletion in mouse models of sepsis is associated with mortality, and the loss of platelets can drive an elevation in plasma pro-inflammatory cytokines (TNFα and IL-6) in septic mice." (PMID 31581214, 2019). "In human sepsis trials, persistently elevated levels of IL-6 correlated with disease severity and an increased risk of death." (PMID 30931316, 2019). "Of all the diagnostic parameters, the best predictor of sepsis in patients with cirrhosis was IL-6, with a diagnostic index (Youden index) of 74.5%." (PMID 31915467, 2019). "The level of IL-6 correlates with the extent of the inflammation, severity of organ dysfunction and sepsis-associated death." (PMID 30760225, 2019). "IL-6 serum concentrations were elevated in the blood of patients with septic disease and IL-6 concentrations were associated with the severity of sepsis." (PMID 31569348, 2019). "In line with these previous studies, we discovered that high expression of lncRNA ITSN1‐2 was associated with increased APACHE II score, CRP, TNF‐α, IL‐6, and IL‐8 levels in sepsis patients." (PMID 30803045, 2019). "The association between IL-6-174 G/C polymorphism and the risk or mortality of sepsis has been widely studied, and previous meta-analyses have been conducted in 2008 and 2013." (PMID 30782124, 2019).
Sepsis (continued). "In this meta-analysis, meta-regression proved that the diagnostic accuracy of IL-6 test for predicting neonatal sepsis with PROM was affected by the types of sepsis (P = .0351)." (PMID 30461611, 2018). "IL-6 andIL-10 cytokine levels were shown to be associated with sepsis prognosis, as theywere higher in the group of patients who died during hospital stay." (PMID 30652781, 2018). "In conclusion, this study showed that high levels of ILT4 in monocytes during sepsis were associated with high serum IL-6 levels and low MHC-II levels on monocytes, resulting in higher mortality of sepsis." (PMID 29662678, 2018). "Little is known about the correlation between HIF-1α and IL-6 in sepsis, however, in colitis-associated colorectal cancer serum concentrations of IL-6 positively correlated with HIF-1α mRNA levels in the tumor tissue." (PMID 30524296, 2018). "It was detected that various genetic polymorphisms, including TNF-α, IL-1, IL-6, and IL- 10, were associated with a predisposition to infection and increased mortality in patients with sepsis." (PMID 28840846, 2018). "In the present study, the specific high ILT4 levels on peripheral blood monocytes during sepsis was associated with high serum IL-6 concentrations and low MHC-II levels on monocytes, leading to poor prognosis." (PMID 29662678, 2018). "When stratified by the rs153109 and rs17855750 genotypes, only the IL-6 concentration was observed to be closely associated with the rs153109 polymorphism in patients with sepsis (P = 0.041)." (PMID 30268141, 2018). "High levels of TNF-α and IL-6 are associated with worse prognoses in septicemia and progression and worsening of RA." (PMID 29924840, 2018). "Because an extremely high level of IL-6 has been reported to be associated with the severity of sepsis and its levels are significantly decreased in the survivors of sepsis, IL-6 is a good prognostic marker for sepsis." (PMID 30297806, 2018). "Patients who suffer from burns, post-major surgery, and those with sepsis have been reported to have increased IL-6 levels, and the peak IL-6 level is associated with the concentration of TNF-α." (PMID 30142934, 2018). "On the other hand, males present predominantly Th1 responses and overproduce tumor necrosis factor α (TNF-Uα), IL-1β, IL-2, IL-6, and IL-8, which in turn are frequently associated with inappropriate outcomes such as sepsis and bacteremia." (PMID 29925409, 2018). "High levels of ILT4 on monocytes were observed in peripheral blood during sepsis and found to be associated with high serum IL-6 levels and low MHC-II levels on monocytes, possibly associated with higher mortality." (PMID 29662678, 2018). "In the pathogenesis of sepsis, three inflammatory hallmark cytokines—Interleukin-6 (IL-6), Interleukin-1β (IL-1β), and tumor necrosis factor-α (TNF-α)—are produced by monocytes and neutrophils." (PMID 29228667, 2017). "NO and overexpressed cytokines, such as tumor necrosis factor-α (TNF-α), interleukin-1β (IL-1β), and IL-6, were also shown to cause sepsis-related systemic inflammation and myocardial depression in sepsis and septic shock." (PMID 29211014, 2017). "First, gender differences in the cord blood IL-6 levels and predisposition to sepsis have been previously reported." (PMID 28531215, 2017). "The IL-6 rs1800795 SNP has been previously associated with sepsis and death, but with discrepant results." (PMID 28247301, 2017). "Sepsis caused high levels of pulmonary myeloperoxidase, elastase, IL6, KC, liver myeloperoxidase, and capillary plugging." (PMID 28789683, 2017). "The increased levels of cry1 in IL-6 KO are paralleling observations in plasma levels of sepsis patients were an increase in IL-6 was associated with a decrease in cry1 mRNA." (PMID 28382017, 2017). "In our cohort, we indeed observed clear associations with sepsis, IL6, CRP, and other inflammation-related biomarkers." (PMID 29180833, 2017).